CX3CR1 (C-X3-C motif chemokine receptor 1)
Diseases named in the same sentence as CX3CR1 in open-access papers (continued):
Sharing a sentence is not in itself a finding about the gene and the disease.
lung carcinoma (26 papers, 2008 to 2025). "An antitumor response driven by the CX3CL1-CX3CR1 axis was evaluated in vivo in a CX3CR1-deficient murine model of melanoma and lung carcinoma." (PMID 39457710, 2024). "Although myeloid cells expression of CX3CL1:CX3CR1 may be linked to tumor-promoting activities such as enhanced growth and migration in lung cancer, CX3CL1:CX3CR1 expression in bulk level is a positive prognostic factor in patients with LUAD." (PMID 40474982, 2025). "Serum CX3CL1 and CX3CR1 levels in the bone metastasis group of primary lung cancer were significantly higher than those in lung cancer patients without bone metastasis or healthy controls." (PMID 40508161, 2025). "Anja Schmall found that the tumor-associated crosstalk between macrophages and cancer cells via the CCR2 and CX3CR1 signaling pathways directed the lung cancer growth and metastasis." (PMID 38514488, 2024). "We and others have previously reported that CX3CR1+CD8+ T cells increase in the peripheral blood of responders to ICI therapy for patients with advanced melanoma or lung cancers." (PMID 36656137, 2023). "Basic experiments have shown that knockdown of CX3CR1 inhibits the proliferation and invasion of lung cancer cells in mice by switching TAMs toward M1 polarization." (PMID 36950551, 2023). "Here, we evaluated the utility of circulating CX3CR1+CD8+ T cells as a predictive correlate of response to chemo-immunotherapy in patients with non–small cell lung cancer (NSCLC)." (PMID 37009132, 2023). "Among them, GIMAP7 was the most significantly downregulated in lung cancer, CX3CR1 was the most upregulated and MYLIP was the most downregulated in systemic sclerosis." (PMID 33691643, 2021). "Downregulation of CX3CR1 can significantly inhibit lung cancer and pancreatic ductal adenocarcinoma cell proliferation and increase apoptosis." (PMID 35003322, 2021). "In in vitro, in vivo, and ex vivo models of lung cancer, TAM-tumor cell crosstalk via the CX3CL1/CX3CR1 axis found to be crucial in lung tumor cell growth, and metastasis, suggesting a potential axis for therapeutic intervention in lung cancer." (PMID 32219066, 2020). "We recently provided evidence that macrophage and cancer cell cross talk via CCR2 and CX3CR1, a fundamental mechanism driving lung cancer." (PMID 26413839, 2015). "Among the gene most strongly down-regulated in NT was CX3CR1, located on chromosome 3p21.3, an area known to be often deleted in lung cancer, particularly in smokers." (PMID 18297132, 2008). "Bidirectional crosstalk between macrophages and tumor cells through CCR2 and CX3CR1 signal transduction might be the driving mechanism of lung cancer." (PMID 36090899, 2022). "IL-10 produced by macrophages induces CX3CR1 expression on lung cancer cells." (PMID 32466280, 2020). "However, a decreased level of CX3CR1 in lung cancer may be related to immune weakness and attenuate cell adhesion, which may be associated with cell metastasis." (PMID 33691643, 2021). "Fully-differentiated Teff (and a subset of CX3CR1+Tems) express IFN-γ and exert cytotoxic activity in patients with lung cancer." (PMID 41203628, 2025). "Co-culturing macrophages with lung cancer cell lines can upregulate CCR2/CCL2 and CX3CR1/CX3CL1 in both cancer cells and macrophages, playing a central role in lung cancer growth and metastasis." (PMID 40264773, 2025). "CX3CL1 and CXCL13 were shown to play an important role in the brain extravasation of breast cancer, while the following cytokines/chemokines were involved in the extravasation of melanoma cells (9IL-23, CXCL10, CXCR3, CXCL10 receptor, CCR4, CCL17, and CCR4) and lung cancer cells (TNF-α and CX3CR1)." (PMID 37190188, 2023). "In addition, the cross-talk between macrophages and cancer cells through CX3CR1 and CCR2 is the basic mechanism resulting to lung cancer." (PMID 35833114, 2022). "For example, exogenous CX3CL1 induces cell migration in H460, but not in H292 and A549, lung cancer cell lines with similar CX3CR1 expression levels." (PMID 33391453, 2021).
lung carcinoma (continued). "IL10 also drives in vivo lung cancer growth and metastasis by upregulating the CCL2/C-C motif chemokine receptor 2 (CCR2) and C-X-C motif chemokine ligand (CXC3CL1)/C-X3-C motif chemokine receptor 1 (CX3CR1) axis in macrophage-tumor cell crosstalk." (PMID 32219066, 2020). "Given that fully-differentiated Teff (and a subset of CX3CR1+Tems) express IFN-γ and exert cytotoxic activity in patients with lung cancer, we sought to identify master regulon(s) that may contribute to CD8+ differentiation along the cytotoxic effector trajectory in NSCLC tumors." (PMID 41203628, 2025). "However, the study found that unspecific inhibition of CX3CR1 might not be a suitable therapeutic option to prevent dissemination of lung cancer cells to the brain." (PMID 37190188, 2023). "In addition, SFRE diminished the expression of PD-L1 and CX3CR1 which exert immunosuppressive effects at the tumour microenvironment, suggesting SFRE may contribute to diminish immune evasion of the lung cancer cells." (PMID 36439419, 2022). "Interestingly, a recent study indicated ﻿that unspecific inhibition of CX3CR1 targeting macrophages/microglia might not be a suitable therapeutic option to prevent brain metastases of lung cancer." (PMID 35194016, 2022).
multiple sclerosis (26 papers, 2006 to 2025). A progressive autoimmune disorder affecting the central nervous system resulting in demyelination. "In a cuprizone-induced demyelination model of multiple sclerosis, CX3CR1-deficient mice exhibit impaired microglial migration and phagocytosis, resulting in persistent myelin debris and defective remyelination with aberrant myelin patterns." (PMID 39940727, 2025). "Consistent with this, in the course of multiple sclerosis, one of the polymorphic variants of CX3CR1, namely, CX3CR1I249/T280, affects the affinity of CX3CL1 for its receptor and the expression of the receptor itself." (PMID 39062768, 2024). "The third key question is whether CX3CR1 pathogenic variants detected in autism spectrum disorder, schizophrenia, and multiple sclerosis contribute to disease pathogenesis via aberrant FKN-CX3CR1 signaling in precursor cells." (PMID 34270934, 2021). "AZD8797 was used in animal studies about multiple sclerosis and liver regeneration to verify the involvement of CX3CR1+ immune cells in disease." (PMID 40458609, 2025). "In the CNS, fractalkine's interaction with its receptor (CX3CR1) can mediate neuron-microglia interactions and has been shown to affect demyelination in multiple sclerosis animal models." (PMID 40373264, 2025). "AZD8797 is a selective CX3CR1 inhibitor, which has been applied in the therapy of the multiple sclerosis model." (PMID 32532282, 2020). "CCR2 and CX3CR1 have been implicated as disease modifiers in EAE, a model for the inflammatory aspects of multiple sclerosis." (PMID 21060874, 2010). "Indeed, CX3CR1 is constitutively expressed in human CNS astrocytes and microglial cells in multiple sclerosis (MS) patients." (PMID 38195526, 2024). "Previous study has suggested that CX3CR1 may be involved in neurodegenerative diseases such as multiple sclerosis, Alzheimer’s disease, spinal cord injury, and traumatic brain injury." (PMID 32532282, 2020). "In addition, the high-affinity small-molecule inhibitor of CX3CR1 (AZD8797) has been investigated in a rat model of multiple sclerosis where it blocked the infiltration of CX3CR1-expressing cells into the central nervous system." (PMID 30845779, 2019). "Notably, microglia may upregulate the CX3CL1/CX3CR1 axis to autoregulate overactivation in pathological conditions like multiple sclerosis." (PMID 40822679, 2025). "Additionally, the CX3CL1/CX3CR1 axis may switch microglia to a neuroprotective type with enhanced phagocytic activity and promote myelin debris clearance and remyelination in multiple sclerosis." (PMID 29311834, 2017). "An animal model of experimentally induced autoimmune encephalomyelitis represents a disease closely related to multiple sclerosis, in which the expression of CX3CL1 and CX3CR1 changes within the sites of demyelination." (PMID 39062768, 2024). "CX3CR1 is involved in the chemotaxis of leukocytes; a previous study revealed a beneficial role of CX3CR1+ NK cells in experimental autoimmune encephalomyelitis (EAE), in a mouse model of multiple sclerosis (MS)." (PMID 36405736, 2022). "To investigate monocyte trafficking in vivo, we generated red fluorescent protein (RFP)-CCR2 knock-in mice, crossed them with CX3CR1-GFP mice, and analyzed them in models of sterile peritonitis and multiple sclerosis using flow cytometry and evaluation of tissue sections." (PMID 21060874, 2010).
COVID-19 (24 papers, 2020 to 2025). A disease caused by infection with severe acute respiratory syndrome coronavirus 2. "CX3CR1 is one of the potential genes associated with COVID-19 and comorbidity, which provides a basis for further guiding drug and vaccine development to improve treatment efficacy and the development of personalized treatments." (PMID 38674036, 2024). "We discovered several chemokine receptor signatures on NK cells (N = 8) associated with the development of severe COVID-19, including upregulated CX3CR1 expression on early NK cells and increased levels of CCR4, CCR9 and CXCR3 on terminal NK cells." (PMID 36433939, 2022). "The expression of CX3CR1 may be associated with the pathological mechanism of severe COVID-19, and the low expression of CX3CR1 in immune cells may contribute to the antiviral response." (PMID 35885892, 2022). "Future studies should therefore determine expression trends through time for CX3CR1 in patients with long COVID-19 compared to patients who fully recover." (PMID 38580667, 2024). "Among them, S100A9, AHNAK, and CX3CR1 have been reported as potential COVID-19 biomarkers previously, and the others (TRAF3IP3 and LFNG) are closely associated with the immune and virus-related signaling pathways." (PMID 35885892, 2022). "Overall, PCA of classical monocytes revealed an acute-phase COVID-19 clustering pattern upon bacterial challenge, which was strongly associated with low expression of HLA-DR, CD86, CD80 and a high expression of CD163, CX3CR1 and CD11b." (PMID 35007290, 2022). "Nevertheless, the frequency of activated CX3CR1+ CD8+ T cells was higher (P=0.056) in adult COVID-19 patients with suspected or confirmed thrombotic complications." (PMID 33653907, 2021). "Frequencies of activated (HLA-DR+CD38+ or Ki67+) CD8+ and CD4+ T cells and activated CX3CR1+ CD8+ T cells remained elevated in MIS-C even when compared to the severe subgroup of pediatric COVID-19." (PMID 33653907, 2021). "In particular, our studies identify a potential relationship between thrombotic complications in adult COVID-19 patients and activation of CX3CR1+ CD8+ T cells." (PMID 33653907, 2021). "Although CX3CR1- T cells were also more activated in MIS-C, the degree of activation and proliferation in CX3CR1+ CD8+ T cells in MIS-C suggested a potential role for increased CD8+ T cell vascular interactions in MIS-C compared to pediatric COVID-19 patients." (PMID 33653907, 2021). "Presently, KAND567 an inhibitor targeting CX3CR1 is in clinical trial for treating COVID-19 hyper-inflammation." (PMID 34867943, 2021). "One of the more striking differences between MIS-C and pediatric COVID-19 was activation of CX3CR1+ CD8+ T cells." (PMID 33653907, 2021). "In the context of COVID-19, peripheral immune profiling has revealed increased CX3CR1 expression on monocytes—suggesting enhanced chemotactic potential and neuroimmune crosstalk consistent with neuroinflammatory features observed in our transcriptomic analyses." (PMID 41007696, 2025). "The activation of CX3CR1+CD8+ T cells is another distinguishing characteristic of MIS-C compared with pediatric COVID-19, which may possibly have consequences in the development of cardiovascular complications." (PMID 36982783, 2023). "S100A9, AHNAK, and CX3CR1 have all been identified as relevant COVID-19 biomarkers." (PMID 35885892, 2022). "Among them, S100A9, AHNAK, and CX3CR1 have been reported to be important biomarkers for COVID-19." (PMID 35885892, 2022). "Moreover, compared to pediatric COVID-19, CX3CR1+ CD8+ T cells in MIS-C were markedly more activated, and a substantially higher proportion were Ki67+ and PD-1+." (PMID 33653907, 2021). "In our study, individuals recovered from severe COVID-19 had increased expression of lung-homing chemokine receptors CCR4, CXCR3 and CX3CR1 on NK cell subsets." (PMID 36433939, 2022).
COVID-19 (continued). "(a) UMAP representations of immune cell populations from healthy participants and COVID-19 patients annotated by cell types (left) and differential expressions of counter receptors ITGAL, SELPLG, and CX3CR1, which are known to interact with surface molecules of activated endothelial cells (right)." (PMID 33752798, 2021). "This approach identified an increase in cells in several clusters, including clusters 1, 2, and 5 in COVID-19 patients, reflecting CD45RA+CD27−CCR7− EMRA-like populations that expressed CX3CR1 and varying levels of T-bet (“EMRA” denotes a subset of effector memory T cells reexpressing CD45RA)." (PMID 32669297, 2020). "Activated CX3CR1+ CD8+ T cells and activated HLA-DR+ CD38+ or Ki67+ CD8+ and CD4+ T cells are found to be more abundant in MIS-C than in patients with severe pediatric COVID-19, but HLA-DR+CD38+ CD8+ T cells frequencies decreased in the first two weeks of admission in MIS-C." (PMID 36982783, 2023). "This corroborates with our data where, contrary to CCL2, serum CX3CL1 was quicky augmented suggesting that non-classical monocytes (NC; CD14+/-CD16++/CX3CR1+) rather than classic monocytes (CL; CD14++CD16−/CCR2+) are the first actors during COVID-19." (PMID 40710346, 2025). "The overall frequencies of CX3CR1+ CD4+ and CD8+ T cells were not increased in MIS-C compared to pediatric COVID-19." (PMID 33653907, 2021). "Although activation of CX3CR1+ CD8+ T cells was highest in MIS-C, this pattern was also observed in some non-MIS-C pediatric and adult COVID-19 patients." (PMID 33653907, 2021).
pulmonary fibrosis (24 papers, 2017 to 2025). Chronic progressive interstitial lung disorder characterized by the replacement of the lung tissue by connective tissue, leading to progressive dyspnea, respiratory failure, or right heart failure. "In a murine experimental model of bleomycin-induced lung fibrosis they demonstrated a significantly lower degree of fibrosis in CX3CR1-deficient mice compared to wild-type mice." (PMID 34208027, 2021). "We thus further analyzed the variations in CX3CR1 expression levels within NK cells according to the clinical characteristics of patients and found a positive association with the pulmonary fibrosis and anti-topoisomerase 1 antibodies." (PMID 30072999, 2018). "Although the role of FKN in the pathogenesis of lung fibrosis is unclear, a study in mice model revealed that bleomycin (BLC)‐induced lung fibrosis is associated with upregulation of CX3CR1 on fibroblasts and M2‐type macrophages, which play a critical role in fibrosis." (PMID 39392260, 2024). "To investigate the function of Axl in MoMs, we constructed Cx3cr1‐Cre::Axlfl/fl mice and examined the formation of pulmonary fibrosis after BLM administration." (PMID 39779468, 2025). "Correspondingly, we used Cx3cr1‐Cre mice to mediate Axl knockout in the monocytes/macrophages and investigate its impact on pulmonary fibrosis." (PMID 39779468, 2025). "CX3CR1 regulates macrophage autophagy, promoting hyperoxia-induced lung injury and pulmonary fibrosis, with silencing alleviating lung fibrosis." (PMID 39768150, 2024). "In mice, local Cx3cl1 in response to bleomycin promotes pulmonary fibrosis by attracting Cx3cr1-expressing M2 macrophages and fibrocytes." (PMID 39768150, 2024). "In a hyperoxia-induced pulmonary fibrosis mice model, elevated CX3CR1 regulates macrophage autophagy and pulmonary fibrosis through the Akt1-signaling pathway." (PMID 39768150, 2024). "The CX3CL1-CX3CR1 axis is associated with pulmonary fibrosis in systemic lupus erythematosus (SLE), with increased CX3CR1 in PBMCs predicting disease progression." (PMID 39768150, 2024). "We found a profound accumulation of CX3CR1-positive macrophages in the lungs of lupus mice after the application of P140, accompanied by lung fibrosis formation." (PMID 37922035, 2023). "A profibrotic effect of the CX3CR1+ transitional macrophages localized to the fibrotic niche was demonstrated in BLM-induced lung fibrosis." (PMID 36934284, 2023). "A previous study showed that in bleomycin-induced pulmonary fibrosis model, CX3CR1 expression was mainly detected in the majority of macrophages and in a small portion of α-smooth muscle actin (αSMA)-positive cells in the lung." (PMID 35222428, 2022). "In fact, we also demonstrated that macrophages expressing CX3CR1 were also positive for the M2-specific marker CD206 in the lungs of the bleomycin-induced pulmonary fibrosis model." (PMID 36434083, 2022). "Several studies showed that high expression of CX3CR1 resulted in the exacerbation of obstruction-induced renal fibrosis and bleomycin-induced pulmonary fibrosis." (PMID 35222428, 2022). "In BLM-ILD, the depletion of CX3CR1-expressing cells suppressed lung fibrosis and this was accompanied by a decrease in infiltrated macrophages." (PMID 34067842, 2021). "Rosa26LSL-DTA mice reduces lung fibrosis, although as we show here, this will also target CX3CR1+ cells destined to become monocyte-derived alveolar macrophages." (PMID 34797692, 2021). "Although the inhibition of CX3CL1 only negligibly affected lung fibrosis, marked changes were observed in CX3CR1+ cells that had abundantly infiltrated the alveolar space." (PMID 34067842, 2021). "The potential role of macrophages in pulmonary fibrosis (PF) prompted us to evaluate the roles of CX3CR1, a chemokine receptor abundantly expressed in macrophages during bleomycin (BLM)-induced PF." (PMID 29203799, 2017).